GABRP (gamma-aminobutyric acid type A receptor subunit pi)
Diseases named in the same sentence as GABRP in open-access papers (continued):
Sharing a sentence is not in itself a finding about the gene and the disease.
tumor (continued). "Studies have also found that GABRP may affect treatment response by regulating tumor metabolic reprogramming or synergizing with immune checkpoint molecules (such as PD‐L1)." (PMID 40459297, 2025). "Therefore, the first approach for cancer treatment is to knock out the expression of the GABRP gene in tumor cells to release GABA." (PMID 40459297, 2025). "It is worth noting that this trend is consistent with the results of functional experiments (GABRP knockdown inhibits tumor growth) and pathway enrichment, suggesting that its potential clinical significance needs to be verified in a larger cohort with clear molecular typing." (PMID 40459297, 2025). "Its cancer‐promoting phenotype needs to be verified through in vitro experiments (such as inhibition of tumor cell proliferation/migration after knocking down GABRP) and in vivo models (delayed growth of mouse transplanted tumors) to clarify the biological basis of clinical association." (PMID 40459297, 2025). "Why is it that only the GABRP gene regulates the complex tumor microenvironment in pan‐cancer?" (PMID 40459297, 2025). "First, GABA receptor inhibitors (such as bicuculline and biculin) may inhibit tumor progression by blocking GABRP‐mediated signal transduction (such as PI3K/AKT or STAT3 pathways)." (PMID 40459297, 2025). "In addition, GABRP is positively correlated with the density of macrophages in the tumor." (PMID 40900801, 2025). "Additionally, GABRA3 may not be the only receptor, and crosstalk with the other GABA receptors, such as GABRP may be occuring; alternatively, there could be other regulatory genes that may also contribute to ECM-associated BRCA tumor progression." (PMID 40583063, 2025). "Several of the uniquely upregulated genes are previously shown to be involved in tumor cell proliferation such as UBE2C, GABRP, and FOXC1." (PMID 39198859, 2024). "Furthermore, GABRP interacts with KCNN4 and stimulates the Ca2+-NF-κB signaling pathway, leading to increase tumor cell growth, macrophage aggregation and tumor invasiveness." (PMID 40900801, 2025). "Bioinformatics analysis showed that TRIB3 and FABP1 may interact with CEACAM5, PRAP1, GABRP, and THBS4, and affect tumor immune microenvironment by regulating immune cells, and participate in the development and progression of GC." (PMID 34957220, 2021). "TRIB3 and FABP1 may interact with CEACAM5, PRAP1, GABRP and THBS4, and affect tumor immune microenvironment by regulating immune cells, and participate in the development and progression of GC." (PMID 34957220, 2021). "For example, expression of GABRP is higher in TNBL tumours than in TNnonBL tumours, supporting previous research suggesting that GABRP is involved in the initiation and progression of BL tumours." (PMID 28981577, 2019). "Although the DNA methylation at the −963 CpG site of the GABRP promoter was not significantly altered in early-stage primary tumor tissues, it was reduced in advanced-stage primary tumor tissues, compared with that of normal tissues." (PMID 28524180, 2017). "Regardless of lymphatic invasion, the average GABRP expression was higher in the advanced stage than in the early-stage tumor tissue, but the differences were not significant in either subgroup, with lymphatic invasion (P=0.664) or without lymphatic invasion (P=0.303)." (PMID 28524180, 2017).
cancer (16 papers, 2009 to 2025). A tumor composed of atypical neoplastic, often pleomorphic cells that invade other tissues. "Pan‐cancer bioinformatics analysis (TCGA, GEPIA2, cBioPortal) assessed GABRP expression, survival associations, and immune infiltration across 33 cancers." (PMID 40459297, 2025). "The TCGA database revealed the mutation frequency of GABRP across various cancer types in the context of pan‐cancer." (PMID 40459297, 2025). "Its functional diversity positions GABRP as a potential diagnostic biomarker and a promising therapeutic target in cancer treatment." (PMID 40459297, 2025). "Its diverse functions make GABRP a potential diagnostic marker and possible therapeutic target for cancer." (PMID 40459297, 2025). "The ERK 1/2 signaling pathway has been implicated in several cancer subtypes 89,101,102; therefore, abnormal manipulation of this pathway by GABRP can result in carcinogenesis." (PMID 34790061, 2021). "GABRP has the potential to serve as a diagnostic marker as well as a possible therapeutic target in cancer." (PMID 34790061, 2021). "Expression of GABRG3, GABRQ, GABRE, and GABRR2 is correlated with inhibition of growth phenotypes in cell lines and with favorable patient outcomes (Broad Institute of MIT & Harvard, firebrowse.org), while expression of other transcripts (GABRB2, GABRP) is associated with cancer progression." (PMID 33187258, 2020). "Using the GEPIA2 database, we performed an online analysis of GABRP expression across various common cancer types and corresponding adjacent normal tissues." (PMID 40459297, 2025). "The γ‐aminobutyric acid receptor π subunit (GABRP) is aberrantly expressed in cancers, but its role in immune evasion is poorly defined." (PMID 40459297, 2025). "In vitro functional experiments further verified its cancer‐promoting mechanism: knocking down GABRP inhibited cancer cell proliferation (CCK‐8 experiment)." (PMID 40459297, 2025). "Expression data showed that GABRP expression increased in cancer patients compared to that in the normal samples presented by the box-whisker plot." (PMID 35846884, 2022). "Sizemore and colleagues found a strong correlation between GABRP and the formation, migration, and aggressiveness of secondary cancer cells, thus implicating GABRP in brain metastases and poor prognosis." (PMID 34790061, 2021). "Pharmacological deletion of macrophages by liposomal clodronate greatly reduced the cancer proliferation of GABRP in PDAC cells." (PMID 34790061, 2021). "Small interfering RNA-mediated GABRP knockdown in PDAC cells was shown to significantly reduce cancer cell proliferation." (PMID 34790061, 2021). "Although this review summarizes our current knowledge of the GABRP and its enigmatic role in cancer, there are still several areas that require thorough research." (PMID 34790061, 2021). "Since target expression in normal tissues is a potential indicator of systemic toxicity, we examined GABRP mRNA expression in normal and cancer tissues and compared with targets of ADCs already showing success in the clinic." (PMID 31624295, 2019). "Basal-A lines were characterized by expression of PROM1 (aka CD133), a marker of various cancer stem cells, as well as other genes like GABRP and VTCN1." (PMID 19582160, 2009). "Emerging evidence suggests that targeted suppression of GABRP gene expression in cancer cells or pharmacological intervention with GABA‐A receptor inhibitors could enable effective and precise immunotherapeutic strategies against cancer." (PMID 40459297, 2025). "Studies have shown that the expression of the GABRP gene is not only involved in the functional regulation of the central nervous system but also plays an important biological role in the occurrence and development of cancer." (PMID 40459297, 2025). "Furthermore, based on retrospective studies we found that among 16 GABA receptors, GABRA3 was significantly upregulated during BRCA advancement, whereas GABRP was downregulated in the later stages of cancer." (PMID 40583063, 2025).
cancer (continued). "More importantly, although conventional chemotherapeutic agents such as paclitaxel and doxorubicin can induce the enrichment of cancer stem cells, knockdown of GABRP reverses this effect, suggesting that GABRP is one of the key mediators of chemotherapy resistance." (PMID 40837580, 2025). "Additionally, the overexpression of GABRP acts as a “silencer,” negatively regulating neural impulses and immune cell activity, thereby promoting immune evasion in pan‐cancer." (PMID 40459297, 2025). "RNAseq data offered a comparison of GABRP among different cancer cell lines and organs." (PMID 35846884, 2022). "Although several studies have already highlighted the role of ERK in cancer, there are several factors that could potentially modulate this pathway; GABRP being one of them." (PMID 34790061, 2021). "Therefore, this review highlights the existing knowledge of GABRP expression and function in healthy individuals and its potential role in cancer." (PMID 34790061, 2021). "The distribution of GABRP mRNA expression across many cancer types suggests that an anti-GABRP-ADC may have therapeutic activity in subsets of several currently difficult-to-treat cancers including gastric, colorectal and lung." (PMID 31624295, 2019). "Therefore, irregularities in ERK 1/2 activation due to GABRP can result in cancer." (PMID 34790061, 2021). "Regarding cancer stem cells, the π subtype of the GABA receptor (GABRP) is highly expressed on the membrane surface of triple-negative breast cancer stem cells." (PMID 40837580, 2025). "Throughout cancer staging, TCGA database showed consistent reduction in expression levels of GABRA2, GABRE, GABRG1 and GABRP by up to 32.7%, 18.7%, 15.4% and 5.9%, respectively." (PMID 40583063, 2025). "Based on the drug information, 29 sex-biased mRNAs were drug-targeted genes and six (CD38, PGR, ESR1, GABRP, F3, PRKCB) of them were targeted by cancer therapeutic drugs." (PMID 39175079, 2024). "Then, an effective method to treat cancer is to continuously inhibit the expression of the GABRP gene or use GABA receptor inhibitors in the growth sites of human cancer cells, which may produce a certain immune targeted treatment effect on cancer cells." (PMID 40459297, 2025). "Interestingly, qPCR also showed that GABRP expression was down-regulated (67.8 %, 103 in 152, P < 0.0001) and ESR1 expression was up-regulated (53.3 %, 81 in 152, P = 0.008) in these cancer tissues compared with their corresponding adjacent normal tissues." (PMID 25990390, 2015).
GABRP also shares sentences with these, for which no sentence is quoted: alcohol dependence (1 paper); autism (1); autoimmune disease (1); cardiomyopathy (1); diabetes (1); insomnia (1); kidney cancer (1); lung adenocarcinoma (1); metastatic cancer (1); ovarian tumors (1); serous ovarian cancer (1).